H4C9 (H4 clustered histone 9)
Description:
Core component of nucleosome. Nucleosomes wrap and compact DNA into chromatin, limiting DNA accessibility to the cellular machineries which require DNA as a template. Histones thereby play a central role in transcription regulation, DNA repair, DNA replication and chromosomal stability. DNA accessibility is regulated via a complex set of post-translational modifications of histones, also called histone code, and nucleosome remodeling.
Synonyms: H4/M; H4FM; HIST1H4I; H4M; TEBIVANED4; TEVANED4
Target class: Other nuclear protein
Gene: Protein-coding gene on chromosome 6 (27,139,282 to 27,140,640, forward strand). Ensembl gene ENSG00000276180.
Subcellular location: Nucleus; Chromosome
Pathways (Reactome):
Gene expression (Transcription): B-WICH complex positively regulates rRNA expression; DNA methylation; ERCC6 (CSB) and EHMT2 (G9a) positively regulate rRNA expression; MLL4 and MLL3 complexes regulate expression of PPARG target genes in adipogenesis and hepatic steatosis; NoRC negatively regulates rRNA expression; PRC2 methylates histones and DNA; RNA Polymerase I Promoter Escape; RNA Polymerase I Promoter Opening; RUNX1 regulates genes involved in megakaryocyte differentiation and platelet function; RUNX1 regulates transcription of genes involved in differentiation of HSCs; Regulation of endogenous retroelements by KRAB-ZFP proteins; Regulation of endogenous retroelements by Piwi-interacting RNAs (piRNAs); Regulation of endogenous retroelements by the Human Silencing Hub (HUSH) complex; SIRT1 negatively regulates rRNA expression; Transcriptional regulation by small RNAs
Chromatin organization: CHD1 and CHD2 subfamily; CHD6, CHD7, CHD8, CHD9 subfamily; ChAHP complex assembly; HATs acetylate histones; HDACs deacetylate histones; HDMs demethylate histones; Interaction of NuRD complexes with transcription factors; NuRD complex assembly; PKMTs methylate histone lysines; RMTs methylate histone arginines
DNA Repair: Cleavage of the damaged purine; Cleavage of the damaged pyrimidine; Nonhomologous End-Joining (NHEJ); Processing of DNA double-strand break ends; Recognition and association of DNA glycosylase with site containing an affected purine; Recognition and association of DNA glycosylase with site containing an affected pyrimidine; Recruitment and ATM-mediated phosphorylation of repair and signaling proteins at DNA double strand breaks
Cell Cycle: Condensation of Prophase Chromosomes; Deposition of new CENPA-containing nucleosomes at the centromere; G2/M DNA damage checkpoint; Inhibition of DNA recombination at telomere; Packaging Of Telomere Ends
Developmental Biology: Activation of anterior HOX genes in hindbrain development during early embryogenesis; Chromatin modifications during the maternal to zygotic transition (MZT); Replacement of protamines by nucleosomes in the male pronucleus
and 20 more pathways
Gene Ontology:
Molecular function: protein binding; RNA binding; structural constituent of chromatin; DNA binding; protein heterodimerization activity
Biological process: negative regulation of megakaryocyte differentiation; nucleosome assembly; chromatin organization; protein localization to CENP-A containing chromatin; telomere organization
Cellular component: CENP-A containing nucleosome; chromosome, telomeric region; extracellular exosome; membrane; nucleoplasm; nucleosome; nucleus; protein-containing complex; extracellular region; chromosome
Genetic constraint (gnomAD): Loss-of-function variants: 3 observed, 4.35 expected, observed/expected ratio (o/e) 0.69, 90% interval 0.31 to 1.64. That is too few expected variants to judge how well the gene tolerates losing a copy. Missense variants: 166 observed, 164.04 expected, observed/expected ratio (o/e) 1.01, 90% interval 0.89 to 1.15. Synonymous variants: 83 observed, 65.48 expected, observed/expected ratio (o/e) 1.27, 90% interval 1.06 to 1.52.
Homologues: Orthologues: pig H4C9 (100% identical). Paralogues in human: H4C1 (100% identical), H4C11 (100% identical), H4C12 (100% identical), H4C13 (100% identical), H4C14 (100% identical), H4C15 (100% identical), H4C16 (100% identical), H4C2 (100% identical), H4C3 (100% identical), H4C4 (100% identical), H4C5 (100% identical), H4C6 (100% identical), and 2 more.
Diseases named in the same sentence as H4C9 in open-access papers:
H4C9 is named in the same sentence as 1 disease in open-access papers, as found by Europe PMC text mining. Sharing a sentence is not in itself a finding about the gene and the disease.
H4C9 shares sentences with these, for which no sentence is quoted: HIV-1 infection (1 paper).